INS (insulin)
Diseases named in the same sentence as INS in open-access papers (continued):
Sharing a sentence is not in itself a finding about the gene and the disease.
Insulin resistance (continued). "Currently, it is known that cytokines such as TNF-α and IL-6 favor insulin resistance through inhibition of the insulin signaling cascade." (PMID 34360849, 2021). "Inflammatory mediators that interfere with metabolic processes, can dysregulate insulin signaling and promote insulin resistance." (PMID 33879088, 2021). "Altogether, the metabolic impact of insulin resistance and impaired insulin signaling in the brain is extensive." (PMID 33845179, 2021). "The pathophysiology of T2D is characterized by insulin resistance combined with a predominant impairment of insulin secretion resulting from the progressive failure of pancreatic β‐cells." (PMID 33855202, 2021). "XM group increased concentrations of FFAs and BHB during exercise and increased insulin and homeostatic assessment of insulin resistance (HOMA-IR) during postprandial periods." (PMID 34959894, 2021). "In conclusion, the denervation results sustained insulin resistance in the soleus but enhanced insulin sensitivity in the EDL due to increased GLUT4 protein levels." (PMID 34066429, 2021). "Insulin resistance is compensated by increased pancreatic insulin production, thus preserving glycemic control." (PMID 34202952, 2021). "Another study found that transplanting the intestinal microbiota of lean donors into patients with metabolic syndrome improved their insulin sensitivity, implying that the intestinal microbiota is involved in the control of body weight and insulin resistance." (PMID 33746902, 2021). "Our results from adipocyte-specific deletion of ILK were consistent with previous studies in muscle and liver, suggesting an important role of the ECM-integrin-ILK pathway in promoting insulin resistance in insulin-sensitive tissues of mice on a HF diet." (PMID 33647469, 2021). "T2D is characterized by impaired function of the islet β-cells that secrete insulin, and resistance to the actions of insulin in peripheral tissues (i.e., insulin resistance)." (PMID 34418413, 2021). "More specifically, PPAR-γ activation in skeletal muscle can have an important protective effect on glucose homeostasis and insulin resistance, because muscle cells secrete functional adiponectin in a PPARγ-dependent manner, improving insulin sensitivity." (PMID 33918414, 2021). "This is particularly important during sleep, in which anti-insulin hormones gradually induce a state of insulin resistance that peaks at dawn." (PMID 33419065, 2021). "Insulin resistance (IR) arises when tissues fail to respond to insulin, and it leads to serious health problems including Type 2 Diabetes (T2D)." (PMID 33479282, 2021). "Even though there is ample evidence about the beneficial effects of OLE on dyslipidemia and insulin resistance in metabolic syndrome, its effects on insulin sensitivity and vascular function in the context of aging has not been studied yet." (PMID 33854149, 2021). "Recent data suggest that insulin resistance in PCOS selectively affects the metabolic action of insulin on pyruvate production by granulosa cells, a mechanism likely to be mediated by the activity of the PI3K/Akt pathway." (PMID 35118400, 2021). "Insulin resistance will decrease FOXO1 phosphorylation by insulin through PI3K-AKT, which would retain FOXO1 in the nucleus and prevent cytoplasmic ubiquitinoylation and degradation, resulting in increased expression of G6pc and Pck1." (PMID 33672754, 2021). "The most important mechanism of action of MF on target cells is the enhancement of the insulin signaling pathways and the decrease in insulin resistance (IR)." (PMID 33429918, 2021). "Fasting plasma glucose, insulin, uric acid levels and an index of insulin resistance (HOMA-IR) increased significantly in the T2D model mice compared with normal ones." (PMID 34698101, 2021). "A higher insulin level in the blood to maintain a normal status of glucose defines insulin resistance." (PMID 34063822, 2021).
Insulin resistance (continued). "Further, in a dose response study in individuals with obesity and insulin resistance, insulin and glucose responses after strawberry intake with a meal were associated with the main anthocyanin metabolite of strawberry, pelargonidin glucuronide." (PMID 32747995, 2021). "Brain insulin resistance impairs synaptic integrity, and tau and Aβ can also interfere with the actions of insulin at synapses." (PMID 34055854, 2021). "TLR4, expressed in insulin target tissues, plays a crucial role in the development of insulin resistance and inflammation." (PMID 34445300, 2021). "A substantial decrease in body weight gain, fat percent, total body fat, serum and liver lipid profile (except high-density lipoprotein), glucose, insulin and insulin resistance in BSTN1 treated rats was noticed in a dose dependent manner." (PMID 34366856, 2021). "Branched-chain amino acids can stimulate insulin secretion, enhance glucose absorption in peripheral blood by muscles, increase the production capacity, and indirectly alleviate insulin resistance, which is conducive to energy supply." (PMID 34007298, 2021). "In type 2 diabetes, insulin resistance is defined as “reduced sensitivity in body tissues to the action of insulin”." (PMID 34576151, 2021). "High insulin resistance and plasma insulin is observed in patients even before hyperglycemia is evident." (PMID 33708999, 2021). "OxS and inflammation strongly induce insulin resistance and additional metabolic disorders, which prompted us to appraise PACs capacity to regulate some key proteins relative to the insulin signaling pathway." (PMID 33594093, 2021). "Ceramides are involved in insulin-mediated glucose uptake and are thought to play an essential role in the development of insulin resistance." (PMID 34573467, 2021). "Another common aspect between metabolic disorder and PTSD is insulin resistance, as the latter is correlated with a slight elevation of insulin concentration, as well as higher insulin responsiveness after performing a glucose tolerance test." (PMID 34966477, 2021). "Insulin resistance is defined as impaired insulin-stimulated glucose uptake in skeletal muscle and adipose tissue stores often combined with impaired insulin-induced suppression of hepatic glucose production." (PMID 32789769, 2021). "Increasing serum levels of xanthine and xanthine oxidoreductase (XOR) has previously shown to be associated with greater production of reactive oxygen species, endothelial dysfunction, body mass index, fasting plasma insulin and insulin resistance." (PMID 34426590, 2021). "Cholesterol absorption inhibitors, such as ezetimibe, appear to increase insulin sensitivity in patients with insulin resistance." (PMID 34940565, 2021). "Particularly, the reduction of insulin-stimulated Akt phosphorylation of serine 473 (Ser473) is considered a reliable indicator of insulin resistance." (PMID 33562475, 2021). "The need for a higher rate of insulin infusion to normalize blood glucose in extremely low birth weight premature infants compared with low birth weight infants also is suggestive of insulin resistance." (PMID 34719946, 2021). "They concluded that insulin resistance in patients with increased liver fat is due to diminished insulin clearance." (PMID 33921359, 2021). "Aging impairs islet β-cell function and insulin secretion, while simultaneously increasing insulin resistance and the incidence of type 2 diabetes." (PMID 33767633, 2021). "Maintaining the insulin secretory function and ameliorating insulin resistance are important in the management of T2DM." (PMID 34489627, 2021). "Vehicle-treated mice on a HFD showed an increase in insulin resistance compared to normal chow fed mice and insulin sensitivity was improved in peptide-treated mice on a HFD." (PMID 34638990, 2021). "In the presence of insulin resistance, skeletal muscle insulin sensitivity is reduced due to impaired IR function and GLUT-4 translocation." (PMID 34502235, 2021).
Insulin resistance (continued). "In fact, we usually define the impairment of insulin effect on glucose metabolism as insulin resistance." (PMID 33816504, 2021). "Additional research can be conducted to further determine the effects of probiotics on insulin resistance and insulin sensitivity among overweight/obese women." (PMID 34603479, 2021). "The metabolic inflammation mediated insulin resistance through the inhibition of insulin signalling, which suppressed the hepatic glucose production or induced the production of ‘‘second messengers’’, such as fatty acids." (PMID 33215869, 2021). "SIK2 phosphorylates p35 priming for the ubiquitin ligase PJA2, which is followed by its proteasome-mediated degradation, which leads to insulin resistance (IR), which results from chronic insulin exposure." (PMID 33923622, 2021). "To investigate the mechanism of insulin resistance-induced damage, we identified the genes affected by excess insulin treatment using transcriptome analysis." (PMID 34358068, 2021). "The high TNF‐α level is a critical common characteristic in insulin resistance in adipocytes and peripheral tissues by destroying the insulin signaling that resulting in the development of T2D." (PMID 34272768, 2021). "It is believed that elevated plasma glucose levels due to peripheral insulin resistance stimulate β cells to elicit a compensatory response to increase the levels of insulin." (PMID 34680372, 2021). "In Type 2 diabetes (T2D), defects in insulin action results in peripheral insulin resistance and beta-cell compensation, ultimately leading to dysfunctional ISG production and secretion." (PMID 33946444, 2021). "IGF-1 is a polypeptide protein substance structurally similar to insulin, and its insufficient expression or abnormal phosphorylation would lead to insulin resistance." (PMID 34899946, 2021). "Comparing pre- and post-treatment with nano-curcumin values revealed a significant decrease in fasting plasma glucose (FPG) (p=0.017), insulin, homeostatic model assessment of insulin resistance (HOMA-IR) (p=0.006), and afamin (p=0.047)." (PMID 33907673, 2021). "Insulin resistance (IR) is a state of decreased tissue sensitivity to insulin, a glycemic-lowering hormone." (PMID 34132976, 2021). "Insulin resistance is defined as insulin inability to perform metabolic and vascular tasks in target tissues." (PMID 33918360, 2021). "This suggests that insulin secretion is less sufficient to compensate for insulin resistance in this group." (PMID 33527668, 2021). "In rats, a continuous insulin infusion leads to development of insulin resistance and hypertension along with higher plasma ET-1 levels." (PMID 34966295, 2021). "The insulin indices calculated were the homeostasis model assessment of insulin resistance (HOMA-IR) and the insulin sensitivity index (ISI)." (PMID 33709001, 2021). "Insulin treatment was incorporated into the study in order to implement a model for insulin resistance, defined as normoglycemia reached by hyperinsulinemia, a condition often observed in obese and prediabetic patients." (PMID 33690729, 2021). "In a previous study, we noted that LXA4 also enhances Pdx expression, prevents STZ-induced type 2 DM, enhances insulin sensitivity, and lowers insulin resistance, results that are like those seen in the present study." (PMID 33546300, 2021). "The possible reason is that sleep deprivation causes the imbalance of the sympathetic vagus nerve, which leads to the decrease of β cell response ability, the inhibition of insulin secretion, and the further development of insulin resistance and T2DM." (PMID 33834077, 2021). "BMPER depletion in ECs also resulted in hepatic and peripheral insulin resistance, indicated by clamp and insulin signaling studies." (PMID 33772019, 2021). "Accumulation of endogenous MGO reduces IRS-1/PI3K association and alters PI3K activity in adipose tissue, leading to decreased insulin stimulated glucose uptake and insulin resistance." (PMID 34966295, 2021).
Insulin resistance (continued). "In controlled studies in NAFLD, bloodletting or a low-iron diet improved insulin resistance and reduced plasma levels of insulin." (PMID 34300354, 2021). "Autophagy was diminished in mice fed a HFD to induce insulin resistance, but when insulin was inhibited chemically with streptozotocin, autophagy was restored." (PMID 35174209, 2021). "Increased intracellular fatty acid metabolites contribute to insulin resistance by impairing insulin-signaling pathways." (PMID 34831705, 2021). "Insulin resistance is defined as the reduced sensitivity of cells to insulin effects in normal or elevated blood glucose levels." (PMID 34940598, 2021). "Pemafibrate treatment also lowered fasting glucose, insulin and homeostasis model assessment of insulin resistance (HOMA-IR) levels." (PMID 33392801, 2021). "Insulin resistance is defined as an impaired tissue response to insulin stimulation, resulting in the dysfunction of glucose and lipid metabolism." (PMID 34735502, 2021). "ZDF rats are characterized by insulin resistance thus the levels of serum insulin were investigated." (PMID 33681196, 2021). "Pancreatic β cell hyperplasia and hypertrophy occur to stimulate more insulin production and to counteract the increasing insulin resistance." (PMID 34022907, 2021). "Normal pregnancy is diabetogenic due to the increased production of insulin (hyperinsulinemia) and insulin resistance (IR), in order to ensure adequate nutrition for the developing fetus." (PMID 34639709, 2021). "The activated ATMs secrete proinflammatory cytokines and form the inflammatory circuit, which blocks the insulin action of adipocytes and leads to insulin resistance." (PMID 33974568, 2021). "Both obesity and insulin resistance can weaken the insulin utilization rate and lead to an increase in blood glucose levels." (PMID 34485124, 2021). "There is no cure for T2DM currently, the cornerstone of the treatment is reducing insulin resistance and stimulating pancreas to secret more insulin." (PMID 34042263, 2021). "Higher levels of fasting triglyceride were associated with higher levels of glucose, glycated hemoglobin, insulin, and homeostatic model assessment for insulin resistance at baseline." (PMID 34930280, 2021). "These markers included pro-inflammatory adipokines, which regulate insulin sensitivity in other metabolic tissues and coincide with insulin resistance and chronic low-grade inflammation." (PMID 34445033, 2021). "Fgfr4−/− knockout mice exhibited glucose intolerance and insulin resistance, while FGFR4 polymorphisms can increase insulin secretion in mice pancreatic islets." (PMID 34035238, 2021). "AMPK is generally correlated with the increase of insulin sensitivity in the body and decrease of insulin resistance as it is the inhibitor of acute proinflammatory responses through reduced FAO." (PMID 34445300, 2021). "This insulin resistance can occur at multiple levels of insulin signaling and is involved in different mechanisms." (PMID 34069890, 2021). "Despite insulin resistance, blood glucose levels remain at constant physiological levels overnight by a modest and transient increase in insulin secretion just before dawn, which helps to restrain liver/kidney glucose production." (PMID 33419065, 2021). "The use of a p38 inhibitor, improved insulin-dependent glucose transport, indicating a decrease in insulin resistance." (PMID 34069890, 2021). "Insulin resistance promotes the development of cognitive dysfunction by hyperinsulinemia and impaired insulin signaling." (PMID 34576151, 2021). "The pooled analyses indicated that probiotic supplements had positive effects on improving FPG level, insulin level, insulin resistance, and insulin sensitivity, especially in GDM and healthy pregnant women." (PMID 34603479, 2021). "Lipid-induced hepatic insulin resistance is marked by decreased insulin-stimulated glycogen synthase flux and impaired insulin-induced inhibition of glucose production." (PMID 34943836, 2021).
Insulin resistance (continued). "The use of metformin in women with polycystic ovary syndrome (PCO) before conception and during pregnancy reduced serum insulin, insulin resistance and insulin secretion." (PMID 33001231, 2021). "Several studies demonstrated that adequate consumption of probiotics can improve immune responses, insulin resistance, and insulin secretion by modulation of gut microbiota." (PMID 34484126, 2021). "Other factors such as “increased levels of serum cortisol”, “Tumor necrosis factor α (TNF α, ILs e.g., IL-6), can interrupt the insulin signaling pathway and can lead to insulin resistance during normal pregnancy”." (PMID 34055923, 2021). "Insulin resistance and insulin sensitivity were calculated using the homeostatic model assessment of insulin resistance (HOMA-IR)." (PMID 34294853, 2021). "Patients with untreated prolactinomas were shown to have higher serum insulin and homeostasis model assessment insulin resistance (HOMA-IR), as well as lower adiponectin levels and impaired glucose tolerance compared to controls." (PMID 33902531, 2021). "Denervation rapidly induces insulin resistance (i.e., impairments in insulin-stimulated glucose uptake and signaling proteins) in skeletal muscle." (PMID 34066429, 2021). "Potential β-cell failure is preceded by a compensatory phase during which β-cell mass and insulin secretory capacity are increased in order to compensate for obesity-induced insulin resistance." (PMID 35008750, 2021). "If the normal metabolic response to insulin is compromised, a condition known as insulin resistance (IR) arises." (PMID 34330275, 2021). "In women with PCOS, metformin reduces the peripheral insulin resistance, and the decreased insulin level improves hyperandrogenism by upregulating steroid hormone-binding proteins in the liver." (PMID 34053455, 2021). "Insulin resistance upsurges peroxisomal oxidation since insulin is the principal inhibitor of cytochrome P450 4A (CYP4A), a significant enzyme in this pathway." (PMID 34522493, 2021). "The relatively prominent signaling pathways involved in the formation of IR are the pathways of insulin resistance, adipocytokine, insulin, PI3K-Akt, ERK, AMPK, and HIF-1." (PMID 34690773, 2021). "In healthy individuals, skeletal muscle takes up 80 to 90% of glucose in response to insulin, and one of the earliest detectable signs of insulin resistance preceding type 2 diabetes (T2D) is reduced insulin-stimulated glucose uptake in skeletal muscle." (PMID 33647317, 2021). "Insulin resistance, or reduced insulin sensitivity, is a key component of the metabolic syndrome, which includes hypertension, obesity, and dyslipidemia." (PMID 34966295, 2021). "Individuals who are insulin sensitive tend to respond well to either low-fat or low-carbohydrate diets, but those with insulin resistance tend to lose significantly more weight on the latter." (PMID 34684300, 2021). "Among 10 patients with both fasting blood glucose and insulin results recorded, there were 8 out of 17 (47.1%) KS patients had insulin resistance." (PMID 34852815, 2021). "We discovered that HMGCR expression is associated with several adipose tissue metabolic pathways, including insulin signaling and citrate cycle, and increased blood circulating levels of phosphatidylcholines and sphingomyelins, as well as insulin resistance." (PMID 34564389, 2021). "Insulin resistance (IR) is an abnormal physiological state in which the body's response to insulin secreted either endogenously or exogenously is decreased." (PMID 34135959, 2021). "TNF-α plays a critical role in mediating insulin resistance associated with high-fat diet and targeting TNF-α increases insulin sensitivity." (PMID 35082682, 2021). "Insulin resistance indicates the inability or inefficiency of the body to respond well to hormone insulin." (PMID 34209599, 2021). "Insulin resistance where the insulin requirement is high and the glucose levels are maintained by high insulin doses is related to bad glycemic control." (PMID 34577866, 2021).